GLP1R (glucagon like peptide 1 receptor)
Diseases named in the same sentence as GLP1R in open-access papers (continued):
Sharing a sentence is not in itself a finding about the gene and the disease.
Parkinson disease (continued). "Therefore, GLP-1R agonists are currently being intensively studied for their use in the treatment of neurodegenerative diseases such as Alzheimer’s disease and Parkinson’s disease." (PMID 34003475, 2021). "Except for its effects in controlling hyperglycemia in diabetic patients, GLP-1R agonists have been suggested as potential neuroprotective agents for neurologic disorders such as Alzheimer’s disease, Parkinson’s disease, cerebral ischemia, and traumatic injury in preclinical and clinical studies." (PMID 33105690, 2020). "Conversely, targeting microglia-mediated conversion of astrocytes into A1 type with NLYP01, a novel glucagon like peptide 1 receptor (GLP1R) agonist, increases lifespan and reverses the loss of dopaminergic neurons, and behavioral deficits in mouse models of Parkinson's disease." (PMID 30542257, 2018). "Interestingly, up-regulation of the microglial glucagon-like peptide-1 receptor (GLP-1R) was identified as a disease marker in Parkinson’s disease and targeting of GLP-1R with an agonist lead to its down-regulation and the abolishment of microglia-dependent A1 astrocyte conversion." (PMID 31118110, 2019). "This is the case, for example, with exenatide, a glucagon-like peptide-1 receptor agonist used for the treatment of T2DM, whose role is currently being evaluated for the treatment of Parkinson’s disease (PD)." (PMID 30814951, 2019). "The administration of the long-acting GLP-1R agonist exendin-4 (Ex-4) reduced brain damage, protected dopaminergic neurons against degeneration, and improved motor function in a MPTP mouse model of Parkinson’s disease." (PMID 40003982, 2025). "Specifically, GLP-1R agonists can cross the BBB and may serve as neuroprotective agents for Parkinson’s disease and AD." (PMID 32079069, 2020). "GLP-1R agonists, established therapeutics for T2DM, were previously shown to protect cognition; thus, liraglutide and exenatide are currently in clinical trials for AD and Parkinson's disease (PD), respectively." (PMID 31297054, 2019). "This hypothesis is supported by the finding that GLP-1R agonists have also shown neuroprotective effects in non-diabetic patients with Alzheimer’s (AD) or Parkinson’s disease (PD)." (PMID 34093449, 2021).
myocardial infarction (88 papers, 2010 to 2026). Gross necrosis of the myocardium, as a result of interruption of the blood supply to the area, as in coronary thrombosis. "This is of interest, as GLP1R agonists have been implicated in preserving proper cardiac remodelling and shown to be cardioprotective following insults such as myocardial infarcts or ischaemia." (PMID 33200567, 2020). "Hence, the reduction in non-fatal myocardial infarction detected with liraglutide is unlikely to be explained solely by GLP-1 receptor-mediated actions; A better understanding of how GLP-1R activation reduces the risk of myocardial infarction and cardiovascular death is needed." (PMID 36686441, 2022). "Molecular imaging can dynamically monitor the protective effect of GLP-1R on ischemic cardiomyocytes, which brings a new auxiliary method for evaluating the therapeutic effect of myocardial ischemia and myocardial infarction." (PMID 37780209, 2023). "In contrast, meta‐analyses of clinical trials have supported a nominally significant (P=0.043 before adjustment for multiple comparisons) beneficial effect of GLP1R agonism on myocardial infarction." (PMID 34184541, 2021). "The elevated levels of GLP-1 and its receptor GLP-1R were reported as a protective action of vildagliptin in models of diabetic nephropathy and myocardial infarction." (PMID 32102588, 2020). "Liraglutide (Lir) is a glucagon-like peptide-1 receptor agonist that lowers blood sugar and reduces myocardial infarct size by improving endothelial cell function." (PMID 31396081, 2019). "Renal tubular and myocardial GLP-1R expression was increased by DPP-4 inhibition in CKD and acute myocardial infarction, supporting a correlation between inflammation and altered GLP-1R expression." (PMID 31795376, 2019). "GLP-1R agonists are known for the treatment of type 2 diabetes, but have also been shown to be cardio-protective in preclinical and clinical studies by reducing myocardial infarct size and improving ventricular function after ischemia." (PMID 34381364, 2021). "Activation of glucagon-like peptide-1 receptor (GLP-1R) signaling protects against cardiac dysfunction and remodeling after myocardial infarction (MI)." (PMID 30547299, 2020). "It has been known for several years that both GLP-1 receptor (GLP-1R) agonists and dipeptidyl peptidase-4 (DPP-4) inhibitors, which increase endogenous GLP-1, protect cardiomyocytes from acute ischaemic damage and promote functional recovery after experimental myocardial infarction (MI)." (PMID 27079193, 2016). "In the myocardial ischemia/reperfusion (MI/R) study, 18F-FBEM-Cys40-exendin-4 could monitor the dynamic changes of GLP-1R upregulation in the myocardial infarction/ischemia area." (PMID 37780209, 2023). "Indeed, GLP-1 receptor (GLP-1R) agonists and dipeptidyl peptidase-4 (DPP-4) inhibitors, which increase endogenous GLP-1, are widely reported to protect cardiomyocytes from acute ischemia and improve functional recovery after myocardial infarction (MI)." (PMID 26597728, 2016). "Herein we will provide an overview on whether reductions in nonfatal myocardial infarction and ischemic heart disease status are a key component of the improved cardiovascular outcomes in people with T2DM treated with either SGLT2 inhibitors or GLP-1R agonists." (PMID 35832485, 2022).
Alzheimer disease (76 papers, 2011 to 2026). A progressive, neurodegenerative disease characterized by loss of function and death of nerve cells in several areas of the brain leading to loss of cognitive function such as memory and language. "Glucagon-like peptide-1 receptor agonists (GLP-1RAs) are promising candidates for Alzheimer's disease (AD) and Parkinson's disease (PD)." (PMID 42098470, 2026). "Background/Objective: Glucagon-like peptide-1 receptor agonists (GLP-1 RAs) exhibit neuroprotective properties in preclinical models of Alzheimer's disease (AD), reducing amyloid accumulation, neuroinflammation, and insulin resistance within the brain." (PMID 41599176, 2026). "One report found that Semaglutide, a GLP-1r agonist, improved cognitive behavior in a genetic mouse model of Alzheimer disease." (PMID 41400881, 2025). "Glucagon-like peptide-1 receptor agonists are a viable option for the prevention of Alzheimer’s disease (AD) but the mechanisms of this potential disease modifying action are unclear." (PMID 39358806, 2024). "Semaglutide (SEM), a glucagon-like peptide-1 receptor agonist, has garnered increasing interest for its potential therapeutic effects in neurodegenerative disorders such as Alzheimer’s disease (AD) and Parkinson’s disease (PD)." (PMID 38921025, 2024). "Numerous studies have consistently shown that GLP-1R agonists like liraglutide, exenatide, and lixisenatide possess the capacity to mitigate neuroinflammation in models of Alzheimer’s disease (AD), leading to an improvement in cognitive function." (PMID 38002034, 2023). "Experimental models and preclinical studies show beneficial effects of GLP-1R agonism on Alzheimer’s disease’s neuropathological features, including cholinergic basal forebrain nuclei degeneration and cognition." (PMID 36499229, 2022). "Clinical studies elucidating the use of GLP-1R agonists in Alzheimer’s disease and cognitive dysfunction in other conditions." (PMID 35264926, 2022). "For example, the expression of GLP-1R in Alzheimer’s disease, experimental autoimmune encephalomyelitis and depression was found to be decreased in the brain." (PMID 34325647, 2021). "Furthermore, the role of GLP-1R agonists in the treatment of neurodegenerative diseases such as Alzheimer’s disease (AD) and Parkinson’s disease (PD) is being actively explored." (PMID 40520185, 2025). "The high expression in the hippocampus and frontal cortex suggests that GLP-1R agonists could have therapeutic effects on cognitive functions impaired in conditions like Alzheimer’s disease (AD)." (PMID 41226780, 2025). "Whether GLP-1R agonists might be useful clinically for attenuating deterioration of cognitive dysfunction and reducing the progression of Alzheimer's disease remains uncertain." (PMID 39216535, 2024). "We chose to carry out studies initially directed at identification of putative mechanisms linking GLP-1R agonism to attenuation of neurodegeneration using two widely used transgenic mouse models of Alzheimer's disease featuring excessive deposition of amyloid plaques." (PMID 39216535, 2024). "Glucagon-like peptide-1 receptor (GLP-1R) agonists may potentially exert neuroprotective effects against nervous system diseases such as Alzheimer’s disease (AD) and Parkinson’s disease (PD)." (PMID 37232753, 2023). "The GLP-1 receptors (GLP-1R) are expressed throughout the brain, and its signaling has been recognized to exert neuroprotective and neurotrophic effects in various experimental models of neurodegenerative diseases, including Alzheimer's disease, Parkinson’s disease, ALS, and ischemic brain injury." (PMID 36983051, 2023). "Clinical data as well as animal and cell studies indicate that certain antidiabetic drugs, including glucagon-like peptide 1 receptor agonists (GLP-1RAs), exert therapeutic effects in Alzheimer’s disease (AD) by modulating amyloid-β peptide (Aβ) metabolism." (PMID 40362335, 2025).
Alzheimer disease (continued). "Recent research has highlighted the therapeutic potential of glucagon-like peptide-1 receptor agonists (GLP-1RAs) beyond glucose metabolism, particularly in neurodegenerative diseases such as Alzheimer’s disease (AD)." (PMID 40642529, 2025). "Mounting evidence indicates that the potential of GLP-1R agonists, mimicking a 30 amino acid ligand, GLP-1, extends to the treatment of neurodegenerative conditions, with a particular focus on Alzheimer’s disease (AD)." (PMID 38915346, 2024). "For example, it has been demonstrated that activating the GLP-1R with liraglutide, a GLP-1R agonist, partially normalizes the lowered INSR level and altered synaptic structure observed in Alzheimer’s disease." (PMID 37886000, 2023).
diabetic kidney disease (75 papers, 2013 to 2025). Progressive kidney disorder caused by vascular damage to the glomerular capillaries, in patients with diabetes mellitus. "In this review, we have presented the evidence for the beneficial effect of glucagon-like peptide-1 receptor agonists on diabetic nephropathy and detailed the underlying molecular mechanisms involved in its pathophysiology." (PMID 34471642, 2021). "Effects of glucagon-like peptide-1 receptor agonists on experimental animal models of diabetic nephropathy." (PMID 39768655, 2024). "In an animal model of diabetic nephropathy, GLP-1R agonists were able to reduce proteinuria and ameliorate glomerular filtration without modifying blood pressure or body weight." (PMID 38275766, 2024). "In various animal models of non-diabetic kidney disease, metformin, GLP-1R agonists, DPP-4 inhibitors, and SGLT-2 inhibitors were favorable to kidney morphology and function." (PMID 33923115, 2021). "In recent years, multiple actions of dipeptidyl peptidase 4 (DPP-4) inhibitors and glucagon-like peptide-1 receptor (GLP-1R) agonists have been well defined in animal models of diabetic kidney disease (DKD)." (PMID 29607314, 2018). "The GLP-1 receptor (GLP-1R) agonist exendin-4 has been reported to ameliorate diabetic nephropathy in animals." (PMID 23621921, 2013). "In this study we investigated the effect of GLP-1R agonist liraglutide on blood pressure, hydration status, natriuresis and the activity of the renin–angiotensin–aldosterone axis in patients with diabetic kidney disease after a dose of liraglutide compared to placebo." (PMID 38424466, 2024). "Despite the advancements in treatment with sodium-glucose cotransporter 2 inhibitors and glucagon-like peptide-1 receptor agonists, patients with T2DM remain at risk of developing diabetic kidney disease (DKD), which is one of the top 10 causes of death globally." (PMID 38400938, 2024). "Moreover, the link between GLP1-R and cAMP generation has also been investigated with regard to the preservation of function in diabetic kidney disease." (PMID 38053992, 2023). "Recently, new therapeutic classes have improved the management of diabetic nephropathy, which is the main cause of CKD and ESRD worldwide, particularly sodium glucose co-transporter 2 (SGLT2) inhibitors and glucagon-like peptide-1 receptor (GLP-1R) agonists." (PMID 34305821, 2021). "A GLP-1R agonist showed anti-inflammatory effects in diabetic nephropathy." (PMID 23621921, 2013). "GLP-1R activation also inhibited apoptosis in diabetic retinopathy and diabetic nephropathy." (PMID 23621921, 2013). "NEW & NOTEWORTHY Liraglutide, a glucagon-like peptide-1 receptor agonist (GLP-1RA), has renoprotective effect in diabetic kidney disease (DKD)." (PMID 39133777, 2024). "Exploring glucagon-like peptide-1 receptor agonist (GLP1-RA) in renal protection, especially in diabetic kidney disease (DKD), reveals a refined molecular landscape." (PMID 38540270, 2024). "Previous study found that GLP-1R expressed on the renal glomeruli and endothelial cells, and GLP-1R therapy had beneficial effects on diabetic kidney diseases." (PMID 29590132, 2018). "Considering the paucity of new agents to treat kidney disease and the minimal adverse effects of metformin, GLP-1R agonists, DPP-4 inhibitors, and SGLT-2 inhibitors, these anti-diabetic agents could be used in patients with non-diabetic kidney disease." (PMID 33923115, 2021). "The treatments for diabetes and obesity, such as sodium-glucose co-transporter 2 (SGLT2) inhibitors and glucagon-like peptide-1 receptor agonists (GLP-1RA), are emerging as promising treatment options in CKD and diabetic kidney disease (DKD)." (PMID 36831103, 2023). "It would be interesting to investigate how acute GLP-1R activation affects the renal hemodynamics in these mice, furthering our understanding of how GLP-1RA may aid in slowing down the functional degradation in diabetic nephropathy." (PMID 38081921, 2023).
metabolic syndrome (73 papers, 2014 to 2026). A cluster of metabolic risk factors for CARDIOVASCULAR DISEASES and TYPE 2 DIABETES MELLITUS. "What is the underlying factor responsible for alterations in markers associated with glucose dysmetabolism (GLP-1R), dyslipidemia (LDLRAP1), ferroptosis (NFE2L2), and autophagy (SQSTM1)?" (PMID 38915346, 2024). "The aim of this study is to investigate the association of two single nucleotide variants of GLP1R gene, rs2268641 and rs6923761, with excessive weight, metabolic syndrome, anthropometric measurements and selected metabolic parameters." (PMID 36339410, 2022). "Here, using whole transcriptome RNA-Seq of the human postmortem caudate nucleus with AD and chronic hydrocephalus (CH) in the elderly, we found that GLP-1R and select mRNAs expressed in glucose dysmetabolism and dyslipidemia were significantly altered." (PMID 38915346, 2024). "Glucagon-like peptide-1 receptor (GLP-1R) agonists, a class of novel hypoglycemic drugs, have exhibited therapeutic effects on multiple metabolic syndromes through diverse mechanisms, including antioxidant, anti-inflammatory, and immunomodulatory actions." (PMID 39456499, 2024). "These pleiotropic effects are also observed after treatment with glucagon-like peptide-1 receptor agonists, positively influencing the cardiovascular outcomes of patients with metabolic syndrome." (PMID 36677012, 2023). "This variant has been associated with metabolic syndrome and a higher risk of DM2 in the Chinese population and less effective treatment of DM2 with GLP1R agonists." (PMID 37888112, 2023). "Except for improving glycemic control, liraglutide, one of the glucagon-like peptide-1 receptor agonists, has exerted promising therapeutic effects for dyslipidemia." (PMID 36643973, 2022). "In comparison to Glp1r agonist alone, Glp1r/ Gcgr dual agonist (DualAG) exhibited superior glycemic control and improvemed dyslipidemia." (PMID 29065174, 2017). "Therefore, we investigated the effects of adherent exercise, a glucagon-like peptide 1 receptor agonist (GLP-1 RA), or the combination on severity of metabolic syndrome, abdominal obesity, and inflammation following weight loss." (PMID 36841762, 2023). "Therefore, we investigated improvements in metabolic syndrome, abdominal obesity, and low-grade inflammation during exercise, a glucagon-like peptide 1 receptor agonist, or the combination of the two following an eight-week low-calorie diet." (PMID 36841762, 2023). "However, recently GLP1R expression on T-IEL was shown to contribute to metabolic syndrome development in mice." (PMID 34473623, 2021). "Therefore, SGLT2 inhibitors and GLP-1R agonists represent a promising approach to treating HFpEF and metabolic syndrome." (PMID 34595217, 2021). "Our results demonstrate that high-salt diet feeding combined with metabolic syndrome evoked impairment of the coronary microvessel vasodilator function and sustained GLP-1R activation with LIRA improved the capacity for NO-mediated dilation to normalize the regulation of myocardial perfusion." (PMID 32093680, 2020). "Taken together, with the overlap between OA risk factors and the metabolic syndrome, the demonstrated anti-inflammatory activities of GLP-1 in several tissues and the expression of GLP-1R in joint tissues, GLP-1 analogues may be good therapeutic candidates for treating OA." (PMID 35280931, 2022). "The frequencies of GLP1R variants in the group with and without metabolic syndrome." (PMID 36339410, 2022). "Glucagon-like peptide-1 receptor agonists and SGLT-2i already have an established efficacy for weight reduction and management of aspects of metabolic syndrome." (PMID 37770761, 2023). "Among them, eriodictyol can improve dyslipidemia, fatty liver and IR in diet-induced obese mice, promote insulin release through the cAMP/PKA pathway, which is related to the activation of GLP-1R." (PMID 40271065, 2025).
metabolic syndrome (continued). "The effects of the long-term glucagon-like peptide 1 receptor agonist treatment on the metabolic syndrome-like conditions are not yet fully elucidated." (PMID 24423471, 2014). "Activation of the GLP-1R/cAMP/PKA pathway is also crucial in renal protection, with studies in a range of rodent models reporting a reduction in renal inflammation, renal fibrosis, and decrease in renal oxidative stress arising from the toxic milieu induced in metabolic syndrome." (PMID 30532733, 2018).